TLR2 (toll like receptor 2)
Diseases named in the same sentence as TLR2 in open-access papers (continued):
Sharing a sentence is not in itself a finding about the gene and the disease.
tumor (continued). "Heat shock protein 90α (HSP90α) on the surface of TRAPs from malignant effusions of cancer patients and tumor cell lines stimulated CD4+ T cell production of IL-6 via a TLR2–MyD88–NF-κB signal cascade." (PMID 31300052, 2019). "For instance, HSP70+ lung tumor-derived exosomes induce activation of NF-kB and secretion of IL-6, IL-8, and MCP1 by MSCs, in a TLR2-mediated signaling, leading MSCs into a more inflammatory and tumor supportive phenotype." (PMID 29515996, 2018). "We found that silencing of TLR2, but not RAGE, TLR4, or CD24, inhibited the migratory ability of the living cancer cells, indicating that HMGB1 regulates tumor cell invasion through TLR2 in vitro." (PMID 29615080, 2018). "The mechanism of tumor cell survival, expansion and metastasis is binding to TLR-2, TLR-4, TLR-9 and RAGE, which mediates HMGB1-dependent activation." (PMID 30526680, 2018). "It exerts tolerogenic effects by binding to TLR-2 in the tumor-infiltrating myeloid cells to promote immune evasion and tumor progression." (PMID 29970158, 2018). "To understand the effects of the treatments, we assessed the tumor size, histopathology, and the TLR2- and TLR4-mediated inflammatory responses." (PMID 29343281, 2018). "One study showed that TLR2 did not affect the susceptibility to developing CRC in mice, whereas another study showed that TLR2 signaling protects against the development of tumor formation in a mouse model of colitis-induced cancer." (PMID 30065713, 2018). "Ligation of TLR-2 followed by auto- or paracrine signalling by endogenously synthesized IL-8 is centrally involved in LTA-induced tumor cell proliferation." (PMID 28314957, 2017). "Depletion of HSP70-positive EVs and blockade of the HSP70/TLR2 interaction using a specific peptide aptamer diminished the activation and number of MDSCs significantly and inhibited tumor progression in tumor-bearing C57Bl/6 mice." (PMID 28275576, 2017). "TLR2/4 signaling has been reported involving in tumor cell immune escape and tumor progression in inflammatory microenvironment." (PMID 28076322, 2017). "The continuous entry of tumor cells into blood and the rapid death of CTCs suggest the continuously release of TLR2/4 ligands into blood." (PMID 28415700, 2017). "Fanny Chalmin demonstrated that mice tumor-derived exosomal HSP72 induce IL-6 production by MDSCs through activation of TLR2 and its adaptor MyD88, leading to Stat3 phosphorylation and the promotion of MDSC immunosuppressive functions." (PMID 27090786, 2016). "Biglycan protein enhanced tumour cell migration and this was inhibited by neutralizing the biglycan receptors using an anti-TLR2 or anti-TLR4 antibody." (PMID 27295191, 2016). "Not only a TLR3-specific (TICAM-1-dependent) signal but also TLR2 (MyD88) signal in DC triggered the expansion of CD11c+ CD8+ T cells in tumor-bearing mice." (PMID 27619885, 2016). "The enhanced activation of ERK1/2 in biglycan-stimulated tumour cells was abolished by preincubation with U0126 or TLR2 and/or TLR4 inhibitors." (PMID 27295191, 2016). "The expression of TLR4 has been correlated with resistance of human OSCC to chemotherapy, and TLR2 expression was shown to be highly correlated with tumor progression." (PMID 27191981, 2016). "In animal models of HCC and head and neck carcinoma, TLR2 expression in tumor cells correlates positively with tumor progression." (PMID 28116318, 2016). "TGF-β1 produced from whole tumor cells decreases antitumor immunity by DC-tumor FCs even when TLR2 and TLR4 are co-administered." (PMID 27240347, 2016). "miR-154, miR-379, and miR-300 have been shown to be decreased in different types of cancer cells, and they function as tumor suppressors by targeting TLR2, Cyclin B1, and Twist, respectively." (PMID 27070142, 2016). "Nevertheless, these data indicated that targeting TLR2 on HNSCC cells inhibits tumor formation in vivo." (PMID 25846753, 2015).
tumor (continued). "Systemic injection of TLR2/6 agonist Pam2 lipopeptides has induced IL-10 production in mice models which prevented effective anti tumor immunity." (PMID 25965265, 2015). "In a manner similar to the cell lines, dissociated PDX tumor cells were also treated either with α-TLR-2 mAb or isotype control IgG and then subsequently treated with zymosan and implanted into immunodeficient Rag2−/−Il2rg−/− mice." (PMID 25846753, 2015). "As observed with the cell lines, exposure of the primary tumor cells to α-TLR2 mAb inhibited organoid growth, indicating that constitutive activation of the receptor was promoting growth in this context." (PMID 25846753, 2015). "Activation of TLR2 with a yeast-derived ligand of TLR2, zymosan, promoted organoid formation in an ex vivo model of tumor growth, while blockade with anti-TLR2 antibodies inhibited organoid formation." (PMID 25846753, 2015). "Polysaccharide K (PSK) known for its anti-tumor and immuno-modulatory function can also activate TLR2 leading to increased secretion of IFN-γ by γδ T cells on stimulation." (PMID 25132835, 2014). "They demonstrated the inability of DCs to migrate to the tumor microenvironment when treated with Ad vectors expressing thymidine kinase (TK) or FMS-like tyrosine kinase 3 ligand (FLt3L) transgenes in TLR2−/− mice." (PMID 28548063, 2014). "These defined TLR signaling pathways seem difficult to help understand why the activation of some TLRs such as TLR3 inhibits tumor growth but the activation of other TLRs such as TLR2 promotes tumor growth." (PMID 25101092, 2014). "Human NK cells can also directly recognize Mycobacterium bovis via TLR2 and enhance their cytolytic activity against tumor cells." (PMID 25132835, 2014). "Their data highlighted the importance of TLR2 involvement in innate immunity to harness an adaptive anti-tumor immune response in cancer gene therapy with Ad-based vectors." (PMID 28548063, 2014). "TLR2, 3, 4, and 9 are highly expressed on both human microglia in the normal brain parenchyma and tumor-infiltrating microglia." (PMID 25411122, 2014). "Targeting TLR2 leads, directly or indirectly, to the induction of strong anti-tumour immunity, which places TLR2 in a unique position as a promising target for cancer immunotherapy." (PMID 23866094, 2013). "It is clear that TLR2 has a unique position in the regulation of tumour tolerance, cancer progression and metastasis." (PMID 23866094, 2013). "Survival curver was generated by Log-Rank test and the role of TLR2 signalling in tumour invasion and migration was determined by transwell analysis kits." (PMID 23866094, 2013). "The data presented here show that combined TLR2/4-activated DC/tumor overcome immune-suppressive effect of TGF-β1 in comparison to those single activated or un-activated DC/tumor." (PMID 23555011, 2013). "In both tumour and host cells, TLR2 plays a crucial role in the establishment of a tumour-induced immunosuppressive environment." (PMID 23866094, 2013). "Versican V1 knockdown also inhibited TLR2 and vitamin D3 signaling, as well as growth and invasiveness of these tumor cells in the in vitro co-culture." (PMID 23424670, 2013). "Here we report the versican V1 derived from tumor cells enhances hCAP18/LL-37 expression in macrophages through the activation of TLR2 and subsequent vitamin D-dependent mechanisms." (PMID 23424670, 2013). "We performed RNAi knockdown experiments to further assess versican V1 influence on macrophage TLR2/6 activation, hCAP18/LL-37 induction, and subsequent tumor cell proliferation and invasion." (PMID 23424670, 2013). "High levels of miR-143 can inhibit tumour invasion and migration in vitro and in vivo by reducing TLR2 activity." (PMID 23866094, 2013). "In conclusion, our results demonstrate that combined TLR2/4-activated DC/tumor overcome immune-suppressive effect of TGF-β1 in comparison to those single activated or immature DC/tumor in vitro." (PMID 23555011, 2013).
tumor (continued). "The tumor cell secreted versican V1 influences hCAP18/LL-37 mediated in vitro tumor promotion and cell invasion through TLR2/6 activation and vitamin D-dependent mechanisms in macrophages." (PMID 23424670, 2013). "Krestin, a TLR2 agonist polysaccharide isolated from mushrooms, mediates the inhibition of tumor growth through immune stimulation." (PMID 24191166, 2013). "We also observed that BMDM differentiated from the BMC of orlistat-administered tumor-bearing mice showed augmented phagocytosis, tumoricidal activity, expression of cell surface receptors like CD11c, TLR-2 and production of ROS, NO, IL-1 and TNF-α." (PMID 24349275, 2013). "TLR2 mRNA expression in the SCC tumor center was 7.90±1.76-fold higher (p<0.01) than in normal skin and also higher than in the tumor center of BCCs (1.41±0.35, p<0.001)." (PMID 22808251, 2012). "Toll-like receptor 2/6 (TLR2/6) signaling in tumor cells is regarded as one of the mechanisms of chronic inflammation but it can also mediate tumor cell immune escape and tumor progression." (PMID 22815694, 2012). "We selected the most effective TLR2 activators among the 20 Pam2 lipopeptides and investigated the corresponding anti-tumor response in vivo." (PMID 21533081, 2011). "In some tumor types, TLRs promote tumor proliferation and survival, whereas in others TLR2, -3, and -9 are directly involved in apoptosis." (PMID 22087156, 2011). "In particular, abundant tumor cell-derived substances like hyaluronan fragments together with heat shock proteins are endogenous ligands to TLR2 and TLR4 and trigger M2-like cytokine profile in macrophages." (PMID 21760797, 2011). "The DAMP, HMGB1, has been found to be upregulated in some carcinomas in which it activates TLRs, including TLR2, on immune cells and enhances tumour progression." (PMID 21179035, 2011). "This immune gene expression signal is likely coming from tumor infiltrating immune cells; however, aberrant immune gene expression by ccRCC cells is also contributory, shown by our elevated TLR2 and CXCR4 expression data." (PMID 20502531, 2010). "A recent study has documented that versican can activate tumour-infiltrating myeloid cells through TLR2 and its coreceptors TLR6 and CD14 and elicit the production of proinflammatory cytokines including TNF-α that enhance tumour metastasis." (PMID 20871832, 2010). "Collectively, these findings indicate that intratumoral Staphylococcus pseudintermedius promotes the proliferation and migration of CMT-U27 cells through activation of the TLR2/PI3K/Akt pathway, highlighting a functional link between tumor-associated bacteria and cancer progression." (PMID 41829039, 2026). "Notably, successful infiltration of adoptively transferred tumor-specific T cells required TLR2 deletion in both the transferred cells and the recipient host." (PMID 41931634, 2026). "Furthermore, tumor-derived exosomal heat shock protein 72 enhances MDSC expansion by activating STAT3 via TLR2/MyD88-dependent autocrine IL-6 production, reinforcing an immunosuppressive tumor microenvironment TME." (PMID 40861469, 2025). "Decorin and lumican can suppress growth factor signaling (e.g., TGF-β and EGFR), while biglycan may promote inflammatory signaling through TLR2/4, underscoring their dual tumor-suppressive and tumor-promoting roles." (PMID 41228294, 2025). "The activation of TLR2/TLR4 by HSPs causes the activation of HSF1 signaling followed by NF-kB signaling in DCs, resulting in the release of cytokines (IL-1, IL-6, and TNF) and the release of tumor antigens, which can be processed by APCs." (PMID 41375025, 2025). "However, the phospholipid peroxidation within macrophages results in the proteolytic degradation of TLR2, which impairs their ability to engulf ferroptotic tumor cells and contributes to the development of tumor resistance to ferroptosis therapy." (PMID 40285867, 2025).
tumor (continued). "Immunotherapeutic strategies that block the interaction sites between Hsp70, TLR2, and MerTK could be advantageous for cancer treatment by disrupting the immunosuppressive communication between tumor cells and immune cells." (PMID 39941817, 2025). "Several polysaccharides, including Cantharellus cibarius polysaccharide, Dendrobium officinale polysaccharide, and Cordyceps mili-taris polysaccharide, have been shown to polarize TAMs toward the M1 phenotype by binding to the target receptor TLR2, thereby inhibiting multiple tumor growth processes." (PMID 41235105, 2025). "Recent studies have shown that 1-stearoyl-2-15-HpETE-sn-glycero-3-phosphatidylethanolamine (SAPE-OOH) is an important surface marker of ferroptotic tumor cells and binds to TLR-2 on the surface of macrophages, promoting the phagocytosis of ferroptotic tumor cells by macrophages." (PMID 40055311, 2025). "The hypoxia–HIF1α axis may further reinforce this program, as HIF1α induces xCT in OSA cells, enhances CSPG4 expression, and upregulates TLR2 in tumor and immune cells." (PMID 41375047, 2025). "In particular, TLR2 is expressed at high levels in several cancers, including gastric, pancreatic, breast, and prostate cancer, where its activation induces tumor progression and metastasis through different tumor cell-intrinsic mechanisms." (PMID 41375047, 2025). "Although the precise mechanisms by which TLR2 modulates DC subset functionality, particularly tumor-infiltrating cDC1s, remain incompletely resolved, we demonstrated that SUP3 slows endosomal acidification in cDC1s, delaying antigen degradation and thereby facilitating cross-presentation." (PMID 41291775, 2025). "Furthermore, USP11 deficiency suppressed tumor spheroid formation in response to EGF, HKLM (a TLR2 agonist), and LPS (a TLR4 agonist), whereas USP11 overexpression amplified these effects." (PMID 41419456, 2025). "Furthermore, tumor-derived exosomes enhance glucose uptake via the TLR2 and NF-κB pathways, leading to increased nitric oxide synthase 2 (NOS2) levels, which inhibit mitochondrial oxidative phosphorylation." (PMID 40028322, 2025). "The expressed acute-phase SAA then activates TLR1/TLR2 to induce an inflammatory tumor environment." (PMID 39940756, 2025). "Similarly, Actinomyces co-localizes with colorectal cancer-associated fibroblasts and reduces CD8+ T lymphocyte infiltration within the tumor microenvironment by activating the TLR2/NF-κB pathway, thereby promoting tumor progression." (PMID 39966840, 2025). "Thus, TLR2's role extends beyond pathogen recognition as it actively shapes the tumor microenvironment by fostering inflammation." (PMID 40922674, 2025). "Furthermore, TLR2 signaling promotes the recruitment of immune cells such as regulatory T-cells alongside myeloid-derived suppressor cells (MDSCs), facilitating tumor immune evasion by interfering with the innate immune response mechanisms." (PMID 41157253, 2025). "Tumor cells can exploit TLR2–MyD88/NF-κB signaling for survival, proliferation, and immune evasion." (PMID 41375047, 2025). "MΦ polarization and tumor growth were assessed in vivo with subcutaneous LLC-GFP tumor models and toll-like receptor 2 (TLR2) knockout mice; in vitro assessments were conducted using TLR2 knockout and both LLC-GFP and LN227 lentiviral-mediated knockdown (KD) cells." (PMID 39941817, 2025). "Therefore, the current study aimed to develop a novel TLR2 agonist, Amuc_1100 C-terminal (Amuc_C), a purified membrane protein from Akkermansia muciniphila (A. muciniphila), and evaluate its anti-tumor properties." (PMID 41170411, 2025).
tumor (continued). "Murine models enabled the discovery of immunomodulatory mechanisms for numerous compounds now in clinical development, including demonstration of PSK’s TLR2-mediated immune activation and lentinan’s enhancement of anti-tumor immunity through macrophage activation." (PMID 40806379, 2025). "Studies have shown a strong correlation between IBDs and the progression of CRC, and prior research has also suggested that early administration of TLR2 agonists may serve as an effective treatment strategy to impede tumor progression." (PMID 41170411, 2025). "Notably, HSP72 on the surfaces of tumor-derived exosomes (TDEs) can produce IL-6 to trigger Stat3 activation in MDSCs in a TLR2/MyD88-dependent manner, which subsequently inhibits T-cell differentiation." (PMID 39911383, 2025). "Given that TLRs are closely related to tumor development and grade, we explored whether there is any difference in TLR2 and TLR4 expression patterns between LGGs and HGGs." (PMID 40809181, 2025). "Similarly, tumor-derived factors can impair myeloid cell function via TLR2, contributing to an immunosuppressive microenvironment." (PMID 41291775, 2025). "Of interest, several studies employed both genetically altered mice and in vitro verification with E. coli-derived recombinant SAA proteins, and the results consistently demonstrate the functions of SAA in Th17 differentiation, TLR2 usage and influence to tumor microenvironments." (PMID 39940756, 2025). "However, activation of TLR2 and TLR9 in microglia has been shown to be associated with increased levels of pro-inflammatory signals, phagocytic activity, and suppressed tumor growth." (PMID 38893093, 2024). "Targeting TLR2 might be a promising strategy to reverse immunosuppression and control tumor progression for an improved prognosis." (PMID 38769374, 2024). "In addition, PDT induces the release of heat shock protein 70 (Hsp70), a damage-associated molecular pattern (DAMP) that binds to Toll-like receptors 2 and 4 (TLR2/4) on tumor cells." (PMID 38481994, 2024). "Notably, TLR2 activation can also induce the accumulation of regulatory T cells in the tumor environment, thereby impairing vaccine efficacy." (PMID 39164536, 2024). "Additionally, Tlr2-/-MMTV–Wnt1 (Tlr2-/-Wnt1) mice exhibit markedly reduced tumor formation compared with that of their Tlr2+/+MMTV–Wnt1 (Tlr2+/+Wnt1) littermates, with median tumor-free days of 269 and 137, respectively." (PMID 38347830, 2024). "Additionally, the frequencies of tumor antigen-specific CD8+ T cells were decreased in the TME of TLR2-KO or TLR4-KO mice compared to that of WT mice." (PMID 38792006, 2024). "Activation of TLR2 can promote M2 polarization of TAMs to enhance tumor growth." (PMID 39458936, 2024). "Also, Actinobacillus co-localise with tumour-associated fibroblasts in CRC, while being able to activate the TLR2/NF-κB pathway, thereby reducing CD8 + T lymphocyte infiltration in the CRC microenvironment." (PMID 38331839, 2024). "TLR4 function is similar to TLR2 because of the common signaling checkpoint (MyD88) they share, and activating NF-κB pathway, which could lead to tumor cell proliferation, apoptosis inhibition, and metastasis." (PMID 37283745, 2023). "CXCL10, CXCL5, MMP1, CXCL12, CXCL11, CXCL2, STAT1, IL‐6 and TLR2 were hub genes in network and may promote or inhibit the homing or of immune cells in tumours and immune cell differentiation, bring intratumoral immune heterogeneity." (PMID 36524848, 2023). "In TLR2 deficiency groups, PepO failed to suppress tumor growth, which was consistent with cell apoptosis in vitro." (PMID 37925462, 2023). "Given their published data, it is reasonable to hypothesize that tumor-derived HMGB1 induced by RT elicits endogenous TLR2 signaling and initiate a CD8+ T cell-dependent immune response." (PMID 37112730, 2023). "Interestingly, studies suggest that low expression of TLR-2, 4, 7, and 9 aids in immune evasion and tumor formation in TNBC." (PMID 36992161, 2023).